PRR11 (proline rich 11)
Diseases named in the same sentence as PRR11 in open-access papers (continued):
Sharing a sentence is not in itself a finding about the gene and the disease.
bladder cancer (3 papers, 2024 to 2026). "In bladder cancer, the main alteration of PRR11 was amplification (Amplification = 1.95%, Mutation = 0.73%)." (PMID 40062654, 2025). "PRR11 also associates with immune infiltration in bladder cancer a potential immune-regulatory role that may extend to CRC, though its mechanism remains unclear." (PMID 41602397, 2026). "This network provides insights into the molecular interactions involving PRR11, suggesting that these associated proteins may also play significant roles in the progression of bladder cancer." (PMID 40062654, 2025). "Although Proline‐rich Protein 11 (PRR11) abnormalities are closely associated with carcinogenesis, the precise mechanism of bladder cancer remains unclear." (PMID 40062654, 2025). "In our study, silencing PRR11 suppressed the proliferation of bladder cancer cells, while overexpression of PRR11 enhanced their proliferative capacity, confirming the role of PRR11 in enhancing cell growth." (PMID 40062654, 2025). "To explore the effect of PRR11 on bladder cancer, we constructed PRR11 silencing and overexpressing bladder cancer cell lines." (PMID 40062654, 2025). "Based on bioinformatics analysis and experimental validation, we have thoroughly explored the mechanism and therapeutic potential of PRR11 in bladder cancer." (PMID 40062654, 2025). "In conclusion, PRR11 is a potential oncogene involved in the development and progression of bladder cancer." (PMID 40062654, 2025). "Our study demonstrates that silencing PRR11 can arrest the malignant progression of bladder cancer by inhibiting EMT and blocking the G1/S transition." (PMID 40062654, 2025). "The effects of PRR11 on bladder cancer cells were examined through both in vitro and in vivo experiments." (PMID 40062654, 2025). "In summary, PRR11 affects bladder cancer progression by modulating the G1/S phase transition through the regulation of cell cycle‐related proteins." (PMID 40062654, 2025). "Our study confirmed that PRR11 is overexpressed in bladder cancer tissues, with its expression levels increasing as the tumor progresses." (PMID 40062654, 2025). "Targeting PRR11 may become an effective therapeutic strategy for bladder cancer with critical clinical applications." (PMID 40062654, 2025). "Here, we sought to elucidate the molecular mechanisms of PRR11 in bladder cancer." (PMID 40062654, 2025). "In bladder cancer, tumor tissues exhibited higher PRR11 than normal tissues." (PMID 40062654, 2025). "We speculate that PRR11 may promote bladder cancer progression by affecting the related proteins in the EMT pathway." (PMID 40062654, 2025). "PRR11 is upregulated in bladder cancer and could lead to poor prognosis." (PMID 40062654, 2025). "To further elucidate the molecular mechanisms through which PRR11 influences bladder cancer, we performed GSEA, which confirmed that the cell cycle is the primary pathway through which PRR11 drives cancer progression." (PMID 40062654, 2025). "Thus, PRR11 appears to drive both tumor growth and distant spread by promoting EMT in bladder cancer." (PMID 40062654, 2025).
liver cancer (3 papers, 2022 to 2023). An epithelial or non-epithelial malignant neoplasm that arises from the liver. "PRR11 has been reported to promote the progression of liver cancer, and Kaplan-Meier survival curve analysis revealed that the PRR11 was associated with a shorter survival time (P < 0.01)." (PMID 35154469, 2022). "Among these characteristic genes, DEPDC1, DEPDC1B, PRR11, and TRIP13 were risk factors for liver cancer patients." (PMID 36785674, 2023). "Overall, the results of the current study revealed that AC099850.3 exerted oncogenic effects in liver cancer cells through the PRR11/PI3K/AKT pathway." (PMID 35154469, 2022). "In liver cancer, the genes DEPDC1, DEPDC1B, PRR11, and TRIP13 have been explored in previous studies." (PMID 36785674, 2023). "Meanwhile, DEPDC1, DEPDC1B, CALCRL, PRR11, and TRIP13 were significantly upregulated in liver cancer tissue, yet NGFR was downregulated." (PMID 36785674, 2023).
cholangiocarcinoma (2 papers, 2015 to 2025). A carcinoma that arises from the intrahepatic biliary tree (intrahepatic cholangiocarcinoma) or from the junction, or adjacent to the junction, of the right and left hepatic ducts (hilar cholangiocarcinoma). "Taken together, the current findings support an oncogenic role for PRR11 in cholangiocarcinoma." (PMID 25971332, 2015).
clear cell renal cell carcinoma (2 papers, 2021 to 2024). "However, the relevant biological functions of PRR11 in human clear cell renal cell carcinoma (ccRCC) have not been studied." (PMID 34499617, 2021).
COVID-19 (2 papers, 2025). A disease caused by infection with severe acute respiratory syndrome coronavirus 2. "Similarly, for COVID-19, BCL6, PRR11, and GAS2L1 showed significant positive correlations with hypoxia, cholesterol homeostasis, xenobiotic metabolism, and glycolysis, and negative correlations with oxidative phosphorylation." (PMID 39965013, 2025).
glioma (2 papers, 2016 to 2024). A benign or malignant brain and spinal cord tumor that arises from glial cells (astrocytes, oligodendrocytes, ependymal cells). "Furthermore, the resistance to ferroptosis in recurrent gliomas is predominantly driven by proline-rich protein 11 (PRR11), which maintains DHODH protein stability." (PMID 39624080, 2024). "Cell cycle progression in human glioma U87MG and U251 cells was halted at S/G2/M phase via the Wnt/β-catenin signaling pathway and related genes such as PRR11, Cyclin A, p-CDK2, VEGFR-1/2, p-VEGFR-1/2 and EGFR." (PMID 27613831, 2016).
intraepithelial neoplasia (2 papers, 2015 to 2020). A precancerous neoplastic process that affects the squamous, glandular, or transitional cell epithelium without evidence of invasion. "The intensity of PRR11 staining increased with the progression of HC: 0.12±0.30 in normal bile duct tissues, 0.50±0.43 in intraepithelial neoplasia, 0.97±1.15 in stage I/II, 1.58±0.98 in stage III/IV and 2.83±0.28 in lymph node metastases." (PMID 25971332, 2015).
lymph node metastasis (2 papers, 2015 to 2022). "In 109 BRCA patients and 260 ER+ BRCA patients, PRR11 promotes more lymph node metastasis, higher Ki-67 ratio and endocrine resistance, thus diminishing the overall survival, recurrence-free survival and relapse-free survival." (PMID 36551227, 2022). "Significant correlations were observed between PRR11 positivity and lymph node metastasis and advanced disease stage." (PMID 25971332, 2015). "In a univariate analysis, PRR11 status, tumor size, tumor invasion, lymph node metastasis and disease stage, were significant predictors of tumor recurrence." (PMID 25971332, 2015). "Expression of PRR11 correlated with lymph node metastasis and CA199 level in two HC patient cohorts." (PMID 25971332, 2015).
melanoma (2 papers, 2019 to 2021). A malignant, usually aggressive tumor composed of atypical, neoplastic melanocytes. "In contrast to BCC and SCC, melanoma biopsies proved to be characterized by transcriptional repression of PRR11 and CAMK1D genes, as indicated by the amplification profiles of the expected 247 and 192 bp PCR products, respectively." (PMID 30795533, 2019). "Since c-MYC was unveiled as a protein partner of PRR11 and c-MYC gene was shown to undergo melanoma-specific intron retention, all five intronic miRNA target genes and some additional ones encoding selected protein interactors were, next, examined for intron retention incidents." (PMID 30795533, 2019).
metastasis (2 papers, 2015 to 2022). The spread or migration of cancer cells from one part of the body (where they first appeared) to another. "There was a significant correlations between PRR11 expression and tumor invasion (p = 0.04) and lymph node metastasis (p = 0.048)." (PMID 25971332, 2015). "Moreover, PRR11 positively correlates with clinical stage, tumor size, lymph node metastasis and tumor differentiation, leading to poor overall survival." (PMID 36551227, 2022).
bladder urothelial carcinoma (1 paper, 2023). "However, there are few reports concerning PRR11 with prognostic risk, immune infiltration, or immunotherapy of bladder urothelial carcinoma (BLCA)." (PMID 36739300, 2023).
breast tumors (1 paper, 2020). "Here, we interrogate transcriptome data from primary breast tumors and find that among genes in 17q23, PRR11 is a key gene associated with a poor response to therapeutic estrogen suppression." (PMID 33127913, 2020). "For instance, there was a significant correlation between PI3K/IGF1 gene set signature scores and high PRR11 mRNA levels in clinical cohorts of ER+ breast tumors treated with neoadjuvant letrozole." (PMID 33127913, 2020). "These last two cohorts comprise primary breast tumors, thus suggesting a higher rate of PRR11 amplification in metastatic (in the MBC project) compared to ER+ primary breast tumors." (PMID 33127913, 2020). "Similarly, hallmark gene sets associated with the PI3K/AKT pathway, such as “PI3K_AKT_MTOR_SIGNALING” and “MTORC1_SIGNALING”, were enriched in METABRIC ER+/HER2− breast tumors with PRR11 gain or amplification compared to PRR11 deleted/diploid tumors." (PMID 33127913, 2020).
cervical cancer (1 paper, 2025). A primary or metastatic malignant neoplasm involving the cervix. "The present study thus aimed to investigate the expression of PRR11 in cervical cancer as a diagnostic and prognostic biomarker, and to characterize the associated clinicopathological features." (PMID 39583185, 2025). "The results revealed that PRR11 gene expression in cervical cancer tissues was significantly higher than that in corresponding normal adjacent tissues." (PMID 39583185, 2025). "For this purpose, reverse transcription-quantitative PCR was used to assess the mRNA expression level of PRR11 in 100 cervical cancer and corresponding adjacent normal tissues." (PMID 39583185, 2025). "On the whole, the present study demonstrates that PRR11 is well-expressed in cervical cancer tissues, is related to age and a poor prognosis, and may thus serve as a potential novel biomarker for cervical cancer diagnosis." (PMID 39583185, 2025). "However, the involvement of PRR11 in cervical cancer has not yet been fully elucidated." (PMID 39583185, 2025).
prostate tumors (1 paper, 2021). "Notably, hsa-mir-195 belongs to the miR-195 family and is located on chromosome 17p13.1, and is correlated with proliferation and angiogenesis in prostate tumors by downregulating expression of the PRR11 gene." (PMID 34093635, 2021).
small cell carcinoma (1 paper, 2025). A neuroendocrine carcinoma composed of small malignant cells which are often said to resemble "oat cells" under the microscope. "For example, small cell carcinomas, which have higher invasiveness and metastatic potential, may rely more heavily on EMT‐related mechanisms, with PRR11 potentially playing an important role in this process." (PMID 40062654, 2025).
tumor (25 papers, 2015 to 2026). "It is thus imperative to improve modern diagnostic methods by searching for novel tumor biomarkers, such as proline-rich protein 11 (PRR11), the expression of which is deregulated in various types of cancer and participates in their cellular progression." (PMID 39583185, 2025). "The Roc analysis of CC vs. normal tissues revealed that PRR11 was a good potential diagnostic biomarker for discrimination between CC and non-tumor tissues." (PMID 39583185, 2025). "GSEA suggests that PRR11 is strongly linked to the cell cycle, and silencing of PRR11 can achieve anti‐tumor effects by inhibiting CCNE and blocking the G1/S phase transition." (PMID 40062654, 2025). "Increased expression of PRR11 is associated with deterioration of clinical characteristics, such as tumor pathological grade and prognosis (OS and DFS)." (PMID 36739300, 2023). "The tumor-associated gene PRR11 is the first protein-coding gene identified from human full-length cDNA by the Mammal Gene Collection Project of the US National Health Agency in 2000." (PMID 34659555, 2021). "Targeting PRR11 caused inhibition of cell growth and tumor survival by reversing EMT and inhibiting activity of key regulators involved in cell migration and invasion." (PMID 25971332, 2015). "We also explored the possible mechanism underlying PRR11 promoting cell proliferation and tumor growth of HC." (PMID 25971332, 2015). "According to the present results, PRR11 was likely to promote the cell cycle of tumor cells and might be associated with the prognosis of patients with ES." (PMID 38427643, 2024). "Moreover, positive expression of PRR11 was significantly associated with an aggressive caner phenotype, including tumors with increased amounts of invasion, increased tumor dedifferentiation, and advanced disease stage." (PMID 26252227, 2015). "Therefore, we hypothesize that PRR11 may have diagnostic, prognostic, and targeted therapy applications in various tumor types." (PMID 36739300, 2023). "PRR11, located on chromosome 17q22, has been reported to be closely associated with cell cycle progression and was also demonstrated to participate in various biological processes in tumor cells, including cell invasion, migration, and proliferation, by acting as an oncogene." (PMID 34497684, 2021). "CDC25C, HMMR, and PRR11 exhibited focal areas of increased expression, indicating spatial variation in functional states within the tumor." (PMID 41602397, 2026). "In GSE39582, however, the expression level of PRR11 was lower in tumor tissues than in normal tissues." (PMID 41602397, 2026). "Subsequently, we further investigated the biological role of the PRR11-AKT axis in the tumor behavior of RCC." (PMID 40083925, 2025). "To understand the role of PRR11 in tumor growth, we performed functional enrichment analysis of related genes in the GEPIA database." (PMID 40062654, 2025). "The tumor volume in the shPRR11 group was smaller than that in the control group, indicating that the depletion of PRR11 inhibited tumor growth." (PMID 40062654, 2025). "On the molecular level, PRR11 promotes tumor metastasis by inducing Epithelial‐mesenchymal Transition (EMT)." (PMID 40062654, 2025). "Depletion of PRR11 causes a deficiency of CCNA proteins, leading to cell cycle disruption in S phase and exerting tumor suppressor effects." (PMID 40062654, 2025). "Next, we analyzed tumor recurrence data in GSE13507 and found that PRR11 expression was significantly elevated in the tumor tissues of recurrent patients compared with those of primary tumors." (PMID 40062654, 2025). "To further investigate the impact of the PRR11-AKT axis on RCC tumor behavior in vivo, we established shNC and shPRR11 stable ACHN cells and verified the knockdown efficiency." (PMID 40083925, 2025). "In cutaneous squamous cell carcinoma, PRR11 promotes tumor progression by activating the EGFR signaling pathway." (PMID 40083925, 2025).
tumor (continued). "In subcutaneous tumor-bearing experiments, treatment with the SC79 reversed the PRR11 knockdown-induced reductions in tumor volume and weight, further supporting the establishment of the PRR11-AKT axis." (PMID 40083925, 2025). "By analyzing and processing patient expression data from the TCGA and GEO databases and validating them with RT‐PCR and Immunohistochemistry, we revealed that PRR11 was aberrantly overexpressed in tumor tissues." (PMID 40062654, 2025). "PET/CT imaging showed that tumor activity was significantly reduced in the PRR11 knockdown group, and SC79 treatment reversed the effect of PRR11 on tumors." (PMID 40083925, 2025). "Immunohistochemical staining and Western blotting were used to observe the expression of risk model factors PRR11, KIF11, RACGAP1 as well as the potential common transcription factors YY1, CREB1 and SUZ12 in HCC tissues and para-tumor tissues." (PMID 39530087, 2024). "In the current study, we performed RNA-seq in three tumor cell lines after interfering with PRR11 for the first time." (PMID 36060253, 2022). "For cellular activities, PRR11 knockdown suppressed hilar cholangiocarcinoma cell proliferation, migration, cell-cycle progression and tumor growth in vitro and in vivo." (PMID 36551227, 2022). "It was found that the expression level of PRR11 was related to the diameter of the tumor (χ2 = 5.514, P=0.019), the clinical stage of the tumor (χ2 = 6.598, P=0.010) and lymph node metastasis (χ2 = 5.274, P=0.021), but not with gender or age." (PMID 34659555, 2021). "In subsequent experiments, it was found that silencing the expression of PRR11 expression inhibited the proliferation of tumor cells and the migration of cells in vitro." (PMID 33276775, 2020). "A comparison of the 49 tumor samples revealed only 3 out of 14 ovarian benign lesions cases with PRR11 positivity (21.4% of patients)." (PMID 33276775, 2020). "Silencing of PRR11 expression significantly inhibited tumor growth as determined by both tumor weight and tumor size, as well as the expression of proliferation related indicators (Ki67), in the PRR11-KO inoculated mice compared with the control group." (PMID 25971332, 2015). "PRR11 expression correlated significantly with number of clinicopathological parameters such as T stage, degree of tumor differentiation, and TNM stage." (PMID 26252227, 2015). "Focusing our analysis, a shorter time to recurrence in patients with R0 resections or shorter OS for patients with R1/R2 resections was found for patients with high tumor expression of PRR11." (PMID 25971332, 2015). "Patients with PRR11-positive tumors had inferior time to recurrence compared to that of PRR11-negative tumor (p < 0.001)." (PMID 25971332, 2015). "In cell culture, PRR11 silencing resulted in decreased cellular proliferation, cell migration, tumor growth of QBC939 cells." (PMID 25971332, 2015). "In present study, it was confirmed that PRR11-KO inhibited cell proliferation and migration, as well as induced S-phase arrest, in vitro and transplanted tumor growth in vivo." (PMID 25971332, 2015). "The results revealed that PRR11 mRNA was expressed in 77.5% (62/80 cases) of the tumor tissues." (PMID 39583185, 2025). "Subsequently, we performed validation of the clinical samples, and the PRR11 expression levels of the three patients after recurrence were further elevated compared with those at the initial diagnosis, and the tumor T‐stage and pathological grading also confirmed the progression of the tumors." (PMID 40062654, 2025). "In addition, we established a tail vein lung metastasis model and found that PRR11 silencing significantly suppressed the fluorescence intensity and number of metastatic tumor nodules, and this suppression was significantly counteracted by SC79 treatment." (PMID 40083925, 2025). "In addition, PRR11 has been reported to commonly display extremely high expression levels in solid tumors and it is strongly related to local tumor recurrence and metastasis." (PMID 39583185, 2025).